RN7SL704P (RNA, 7SL, cytoplasmic 704, pseudogene)
Gene: Miscellaneous RNA gene on chromosome 22 (38,231,720 to 38,231,993, forward strand). Ensembl gene ENSG00000241693.
Homologues: Orthologues: chimpanzee Metazoa_SRP (99% identical), macaque Metazoa_SRP (91% identical). Paralogues in human: RN7SL1 (85% identical), RN7SL2 (84% identical), RN7SL3 (84% identical), RN7SL14P (82% identical), RN7SL709P (82% identical), RN7SL45P (81% identical), RN7SL566P (81% identical), RN7SL126P (81% identical), RN7SL186P (80% identical), RN7SL220P (80% identical), RN7SL242P (80% identical), RN7SL386P (80% identical), and 706 more.